NDUFS2 (NADH:ubiquinone oxidoreductase core subunit S2)
Description:
Core subunit of the mitochondrial membrane respiratory chain NADH dehydrogenase (Complex I) which catalyzes electron transfer from NADH through the respiratory chain, using ubiquinone as an electron acceptor. Essential for the catalytic activity of complex I. Essential for the assembly of complex I (By similarity). Redox-sensitive, critical component of the oxygen-sensing pathway in the pulmonary vasculature which plays a key role in acute pulmonary oxygen-sensing and hypoxic pulmonary vasoconstriction. Plays an important role in carotid body sensing of hypoxia (By similarity). Essential for glia-like neural stem and progenitor cell proliferation, differentiation and subsequent oligodendrocyte or neuronal maturation (By similarity).
Synonyms: CI-49; LHONAR2; MC1DN6
Tractability: Small molecule: an approved drug acts on it; a structure with a bound ligand is known. Antibody: UniProt places it where antibodies can reach, with medium confidence. PROTAC: ubiquitination databases record sites on it; its protein half-life has been measured; a small molecule that binds it is known.
Target class: Enzyme; Oxidoreductase
Chemical probes: BAY-179
Gene: Protein-coding gene on chromosome 1 (161,197,104 to 161,214,723, forward strand). Ensembl gene ENSG00000158864.
Subcellular location: Mitochondrion inner membrane
Subcellular location (Human Protein Atlas): Mitochondria; Calyx; Connecting piece
Pathways (Reactome):
Metabolism: Complex I biogenesis; Respiratory electron transport
Gene Ontology:
Molecular function: NADH dehydrogenase (ubiquinone) activity; NADH dehydrogenase activity; oxygen sensor activity; protein binding; ubiquitin protein ligase binding; electron transfer activity; NAD binding; oxidoreductase activity, acting on NAD(P)H; quinone binding
Biological process: cellular response to oxygen levels; mitochondrial ATP synthesis coupled electron transport; mitochondrial electron transport, NADH to ubiquinone; aerobic respiration; gliogenesis; mitochondrial respiratory chain complex I assembly; neural precursor cell proliferation; neurogenesis; proton motive force-driven mitochondrial ATP synthesis; proton transmembrane transport
Cellular component: mitochondrial inner membrane; mitochondrion; respiratory chain complex I; mitochondrial matrix
Genetic constraint (gnomAD): Loss-of-function variants: 38 observed, 72.2 expected, observed/expected ratio (o/e) 0.53, 90% interval 0.41 to 0.69. The upper end of that interval is the gene's LOEUF score, 0.69, which puts it in group 2 of 6, group 1 being the genes least tolerant of losing a copy. Missense variants: 468 observed, 622.65 expected, observed/expected ratio (o/e) 0.75, 90% interval 0.7 to 0.81. Synonymous variants: 194 observed, 222.85 expected, observed/expected ratio (o/e) 0.87, 90% interval 0.77 to 0.98.
Gene-disease validity (ClinGen):
ClinGen rates the evidence that NDUFS2 causes each of these diseases.
Leigh syndrome (autosomal recessive): Definitive. A progressive neurological disease defined by specific neuropathological features associating brainstem and basal ganglia lesions.
mitochondrial disease (autosomal recessive): Definitive.
Homologues: Orthologues: chimpanzee NDUFS2 (99% identical), pig NDUFS2 (95% identical), rabbit NDUFS2 (94% identical), dog NDUFS2 (94% identical), guinea pig NDUFS2 (93% identical), mouse Ndufs2 (92% identical), rat Ndufs2 (92% identical), macaque NDUFS2 (87% identical), tropical clawed frog ndufs2 (81% identical), zebrafish ndufs2 (81% identical), Drosophila melanogaster ND-49 (74% identical), Caenorhabditis elegans gas-1 (65% identical), and 2 more.
Diseases named in the same sentence as NDUFS2 in open-access papers:
NDUFS2 is named in the same sentence as 49 diseases in open-access papers, as found by Europe PMC text mining. Sharing a sentence is not in itself a finding about the gene and the disease. The quoted sentences say what the papers report.
Parkinsonism (7 papers, 2018 to 2024). Characteristic neurologic anomaly resulting from degeneration of dopamine-generating cells in the substantia nigra, a region of the midbrain, characterized clinically by shaking, rigidity, slowness of movement and difficulty with walking and gait. "Most recently, deficiency of Ndufs2 in dopaminergic neurons caused Parkinson's disease‐like phenotypes in mice." (PMID 37029501, 2023). "Disruption of mitochondrial complex I in dopaminergic neurons by deletion of Ndufs2 is sufficient to cause progressive parkinsonism in which the loss of nigral dopamine release and slower or stopped pace-making of dopaminergic neurons mediate motor dysfunction." (PMID 38236644, 2024). "Notably, we identified that CO therapy decreased the expression of genes encoding ETC complex I genes: NDUFB4, NDUFS2, NDUFAB1, NDUFA6, NDUFB9, also enriched in Parkinson’s, Huntington’s and Alzheimer disease pathways." (PMID 31615996, 2019).
Leigh syndrome (5 papers, 2012 to 2025). "Substitutions of E104A, M292T, R118Q, M443K, E148K, and F84L in the NDUFS2 subunit in the Q module lead to Leigh syndrome, while R138Q, R333Q, and M292T mutations of NDUFS2 result in a Leigh-like syndrome." (PMID 39857410, 2025). "Mutations in NDUFS2 are related to mitochondrial complex I deficiency and Leigh syndrome or cardiomyopathy and encephalomyopathy." (PMID 38607042, 2024). "Mutations in NDUFS2 cause severe reductions in CI activity and perturb the formation of CI assembly in patients with Leigh Syndrome." (PMID 36834818, 2023). "In Leigh syndrome patient fibroblasts, with a recessive NDUFS2 mutation, respiration and spare respiratory capacity are increased by prodrug administration." (PMID 27502960, 2016). "Ndufs2 mutations are part of complex I deficiency disorders such as Leigh’s disease and mitochondrial diseases that include encephalopathies, and this gene was identified as a possible modulator of adult neurogenesis in the hippocampus." (PMID 22952935, 2012).
lung carcinoma (4 papers, 2021 to 2023). "In addition, complex I activity could also be increased when its auxiliary subunit is upregulated, given that S100 calcium-binding protein A4 was reported to enhance complex I activity in lung cancer cells by upregulation of NDUFS2." (PMID 37186123, 2023).
pancreatic cancer (4 papers, 2021 to 2025). "It was further verified that NDUFS2 promoted pancreatic cancer cell migration by regulating the expression of E-cadherin and vimentin." (PMID 38653740, 2024). "Further experiments indicated that overexpression of OTUB1 in pancreatic cancer cells increased the expression of NDUFS2, and knockdown of OTUB1 decreased the expression of NDUFS2 in vitro." (PMID 38653740, 2024). "To further substantiate our conclusions, we checked the effect of OTUB1 on endogenous ubiquitination of NDUFS2 in pancreatic cancer cells." (PMID 38653740, 2024). "In this study, we found that NDUFS2 plays a critical role in the proliferation, cell-cycle precession, colony formation and migration of pancreatic cancer cells." (PMID 38653740, 2024). "The result showed that OTUB1, as well as NDUFS2, were abundantly expressed in pancreatic cancers in contrast to the adjacent tissues." (PMID 38653740, 2024). "Statistical analysis indicated that the expression of OTUB1 and NDUFS2 in pancreatic cancers was significantly higher than those in normal pancreatic tissues at transcriptional level." (PMID 38653740, 2024). "Our previous study has demonstrated that NDUFS2 levels were elevated in pancreatic cancer tissues compared to adjacent normal tissues." (PMID 38653740, 2024). "Collectively, those data suggested that NDUFS2 plays an indispensable role in mitochondrial function and homeostasis in pancreatic cancer cells, which determined the cell fate." (PMID 38653740, 2024). "Here, we showed that NDUFS2 inactivation inhibited tumor growth in a mouse xenograft pancreatic cancer model, implicating a potential role of NDUFS2 in the development of pancreatic cancer in vivo." (PMID 38653740, 2024). "NDUFS2 perhaps affecting mitochondrial dynamics and functions in pancreatic cancer cells by altering MMP." (PMID 38653740, 2024). "To further search for the downstream signaling pathways through which NUDT21 promotes pancreatic cancer cell proliferation and migration by interacting with NDUFS2, we validated the PI3K–AKT pathway postulated by GO and KEGG analysis." (PMID 38195952, 2024). "Confocal assay showed that OTUB1 and NDUFS2 were co-localized and upregulated in pancreatic cancer tissues compared to the adjacent normal tissues." (PMID 38653740, 2024). "Here, we showed that NDUFS2 played a critical role in the survival, proliferation and migration of pancreatic cancer cells by inhibiting mitochondrial cell death." (PMID 38653740, 2024). "Collectively, those data suggested that OTUB1 behaved much similarly with NDUFS2 in regulating mitochondrial membrane dynamics and ATP production in pancreatic cancer cells." (PMID 38653740, 2024). "Accordingly, overexpression and knockdown of OTUB1 phenocopied those of NDUFS2 in pancreatic cancer cells, respectively." (PMID 38653740, 2024). "NUDT21 promotes the proliferation and migration of pancreatic cancer cells through the regulation and stabilization of NDUFS2 and activation of the PI3K–AKT pathway." (PMID 38195952, 2024). "In order to find out the possible protein that interact with NDUFS2 in pancreatic cancer, co-immuno-precipitation (co-IP) was carried out to capture NDUFS2 interactors." (PMID 38653740, 2024). "S100 calcium-binding protein A4, a protein related to cancer metastasis, can promote mitochondrial activity and ATP production via upregulating NDUFS2 expression, which is beneficial to the proliferation and invasion of pancreatic cancer SUIT-2 cells." (PMID 33923185, 2021). "Moreover, we found that NUDT21 regulates pancreatic cancer cell proliferation and migration by modulating and stabilizing NDUFS2 and activating the PI3K-AKT signaling pathway through protein mass spectrometry." (PMID 38195952, 2024).
pancreatic cancer (continued). "Taking together, our present study revealed that OTUB1 played a crucial role in the development of pancreatic cancer, and NDUFS2, identified as a substrate of OTUB1, might be responsible for the observed phenotypes in the absence of OTUB1 in pancreatic cancer." (PMID 38653740, 2024). "Considering the importance of OTUB1 and NDUFS2 in mitochondrial metabolism and tumorigenesis, we hypothesized that they may be involved in mitochondrial functions and tumorigenesis of pancreatic cancer." (PMID 38653740, 2024). "NDUFS2, a subunit of mitochondrial complex I, has no reported association with MM we are aware of at this time but has recently been reported to play a role in pancreatic cancer." (PMID 41441334, 2025). "Treatment targeting NDUFS2 may provide us novel approaches for the treatment of pancreatic cancer." (PMID 38653740, 2024). "However, the role of NDUFS2 in pancreatic cancers remains uncovered." (PMID 38653740, 2024). "The primary aim of this study was to investigate whether OTUB1 or NDUFS2 or both of them can be used as new prognostic biomarkers and/or therapeutic targets for pancreatic cancer and shed new lights into exploring therapeutic methods for pancreatic cancer." (PMID 38653740, 2024). "In conclusion, we revealed that OTUB1 increased the stability of NDUFS2 in PAAD by deubiquitylation and this axis plays a pivotal role in pancreatic cancer tumorigenesis and development." (PMID 38653740, 2024). "Then, we filtered all the upregulated and downregulated genes in pancreatic cancer in the online TCGA database, and identified that OTUB1 and NDUFS2 were both upregulated in pancreatic cancer among all the upregulated genes, deciphered by the volcano map." (PMID 38653740, 2024). "In addition, we confirmed that the levels of NDUFS2 and OTUB1 were positively correlated through Co-IP, both of which were abundantly expressed in pancreatic cancer." (PMID 38653740, 2024). "In our previous study, we identified NDUFS2 as a downstream factor of PTPMT1 in pancreatic cancer, but the precise role has not yet been validated." (PMID 38653740, 2024). "We also filtered all dysregulated genes in pancreatic cancer profiles from TCGA database, and we identified all the upregulated genes and downregulated genes; the Volcano map deciphers the localization of NUDT21 and NDUFS2 in PAAD among all the upregulated genes." (PMID 38195952, 2024).
breast carcinoma (3 papers, 2024 to 2025). "Unique mutations in genes such as NDUFS2, MGST3, PRDX6, NDUFS8, and GSTP1 were found predominantly in breast cancer." (PMID 39594421, 2024). "Our analysis revealed that mutations in OSRE such as MGST3, GSTP1, NDUFS2, NDUFS8 and PRDX6 were particularly prevalent in breast cancer, and for the five genes the most prevalent genetic alteration was amplification." (PMID 39594421, 2024). "However, NDUFV2, NDUFS2, and NDUFS3, whose expression levels have little impact on patient survival of any subtype of breast cancer, contain no Fe–S clusters or play no role in the main path of electron transport." (PMID 39873399, 2025).
cardiomyopathy (3 papers, 2012 to 2024). A disease of the heart muscle or myocardium proper. "For example, cardiomyopathy has first been reported as characteristic for the NDUFS2 gene but was later reported in other nuclear complex I genes as well." (PMID 22644603, 2012). "These cardiomyopathies are often associated with mutations in mtDNA encoded Complex I subunit genes NADH-ubiquinone oxidoreductase chain 1 and 5 (MT-ND1 and 5) and nuclear-encoded Complex I subunit genes such as NADH: ubiquinone oxidoreductase core subunits S2 (NDUFS2), V2 (NDUFV2) or A2 (NDUFA2)." (PMID 38020895, 2023). "Moreover, after the first three patients with NDUFS2 mutations with cardiomyopathy, no patients with this combination have been described." (PMID 22644603, 2012).
Leber hereditary optic neuropathy (2 papers, 2021). Leber's hereditary optic neuropathy (LHON) is a mitochondrial neurodegenerative disease affecting the optic nerve and often characterized by sudden vision loss in young adult carriers. "This presentation is consistent with a Leber hereditary optic neuropathy (LHON)-like phenotype, whose existence and association with NDUFS2 and DNAJC30 has only recently been described." (PMID 33918393, 2021).
Non-alcoholic fatty liver disease (2 papers, 2023). "F11r and Fcer1g are found on KEGG pathways primarily related to the immune system while Ndufs2 and Sdhc are found on the Non-alcoholic fatty liver disease pathway (mmu04932)." (PMID 36778219, 2023).
Obesity (2 papers, 2015 to 2022). Accumulation of substantial excess body fat. "Together, these findings reveal a previously unrecognized mechanism for muscle-BAT cross talk driven by Islr, Ndufs2, and IL-6 to regulate energy homeostasis, which may be used as a potential therapeutic target in obesity." (PMID 36077405, 2022). "When we investigated the list of 162 DMRs mapping to annotated loci in further detail we observed other genes with known and potential roles in obesity and related traits (such as PRKCZ, NDUFS2, GATA2, FOXP2, ANGPT2, NCOR2, CPT1B, PTPN6)." (PMID 25651499, 2015).
pancreatic adenocarcinoma (2 papers, 2024). "Our previous study reveals that NDUFS2 (NADH: ubiquinone oxidoreductase core subunit S2), a core subunit of the mitochondrial respiratory chain complex I, is upregulated in Pancreatic adenocarcinoma (PAAD)." (PMID 38653740, 2024). "We screened the expression of NDUFS2 in major human cancer species using the TCGA database and GTEx data, and we found that NUDT21 and NDUFS2 were both significantly higher expressed in pancreatic adenocarcinoma (PAAD) compared to control tissues." (PMID 38195952, 2024).
schizophrenia (2 papers, 2015 to 2021). A major psychotic disorder characterized by abnormalities in the perception or expression of reality. "We observed marginally significant associations with schizophrenia of rs10908826, rs4656994, rs5085 and rs2307424 in the NDUFS2 gene and rs12457810, rs12964485 and rs2377961 in the NDUFV2 gene." (PMID 26053550, 2015). "In addition, Ndufs2 was associated with schizophrenia terms and Scp2 was associated with alcohol-related terms." (PMID 34367237, 2021). "However, we observed nominal significant associations of 2 SNPs in the NDUFS1 gene and 4 SNPs in the NDUFS2 gene with early onset schizophrenia (EOS), but none of these associations survived the Bonferroni correction." (PMID 26053550, 2015).
amnesia (1 paper, 2021). Pathologic partial or complete loss of the ability to recall past experiences ( AMNESIA, RETROGRADE) or to form new memories ( AMNESIA, ANTEROGRADE). "Activation of mitochondrial CB1 receptors resulted in a decrease in PKA-dependent phosphorylation of oxidative phosphorylation proteins, including NDUFS2, and a concomitant decrease in brain mitochondrial function that was associated with cannabinoid-induced synaptic depression and amnesia." (PMID 34367237, 2021).
glioma (1 paper, 2020). A benign or malignant brain and spinal cord tumor that arises from glial cells (astrocytes, oligodendrocytes, ependymal cells). "We established that OSMR directly interacts with NDUFS1/NDUFS2 of complex I in the mitochondria of patient derived glioma stem cells." (PMID 32807793, 2020).
hereditary optic neuropathy (1 paper, 2017). "Mutations in NDUFS2 and NDUFS7, orthologs of nduf-2.2/gas-1 and nduf-7, respectively, are associated with mitochondrial Complex I deficiency, which can cause hereditary optic neuropathy." (PMID 28539870, 2017).
hypertrophic cardiomyopathy (1 paper, 2024). A condition in which the myocardium is hypertrophied without an obvious cause. "In clinical studies, a connection has been established between hypertrophic cardiomyopathy and mutations found in the NDUFS2 and NDUFV2 genes in patients undergoing clinic‐treatment." (PMID 38546629, 2024).
lung adenocarcinoma (1 paper, 2024). A carcinoma that arises from the lung and is characterized by the presence of malignant glandular epithelial cells. "Accordingly, a study conducted by Jeon and colleagues has shown that an elevated expression of OXPHOS-encoding genes, in particular genes of core, accessory, and assembly subunits of Complex I, including NDUFS2 and NDUFA10, correlates with poor prognosis in lung adenocarcinoma patients." (PMID 39000504, 2024).
multiple sclerosis (1 paper, 2008). A progressive autoimmune disorder affecting the central nervous system resulting in demyelination. "In addition we have identified a trend towards an association with the NDUFS2 gene in the Complex I pathway, providing further support that this may be disrupted in multiple sclerosis patients." (PMID 18682780, 2008).
myocardial infarction (1 paper, 2024). Gross necrosis of the myocardium, as a result of interruption of the blood supply to the area, as in coronary thrombosis. "Ventricular expression of 10 central MitoDEGs (Aco2, Atp5a1, Ndufs3, Ndufv1, Cyc1, Suclg1, Sdha, Sdhb, Cs, and Ndufs2) was verified in a mouse model of myocardial infarction using PCR." (PMID 39775580, 2024).
overnutrition (1 paper, 2019). An imbalanced nutritional status resulting from excessive intake of nutrients. "Fatty liver is known to occur in both under- and overnutrition; our results suggest that this might reflect regulatory disruptions in a core set of genes, including NDUFS2 and PHLDA1, that lead to steatosis regardless of the directional effect of the nutritional insult." (PMID 31857576, 2019).
prostate carcinoma (1 paper, 2012). A carcinoma that arises from epithelial cells of the prostate gland. "A recent report has evaluated the role of 376 tagSNPs (one included in our study, rs11576415 in NDUFS2) in 78 nuclear-encoded mitochondrial genes (including ATP5C1, NDUFS2, and UQCR) in prostate cancer risk, without clear evidence of association." (PMID 22545919, 2012).